TLR4 (toll like receptor 4)
Diseases named in the same sentence as TLR4 in open-access papers (continued):
Sharing a sentence is not in itself a finding about the gene and the disease.
liver fibrosis (continued). "Therefore, this study indicates that the protective effects of DOP on hepatic fibrosis might be achieved by protecting the intestinal mucosal barrier and regulating the TLR4/NF-κB pathway." (PMID 32226380, 2020). "Therefore, modulation of TLR4-MyD88-NF-κB signaling might represent a feasible strategy for the treatment of liver fibrosis." (PMID 32296336, 2020). "Emerging evidences suggested that HMGB1/TLR4/NF-κB signaling was firmly associated with the activation of HSCs as well as the synthesis of ECM, and inhibition of HMGB1 could significantly reduce inflammatory response and ameliorate liver fibrosis." (PMID 32425800, 2020). "Therefore, the HMGB1/TLR4/NF-κB signaling pathway plays a pivotal role in liver fibrosis, and modulation of this signaling pathway is an appealing strategy for the inhibition of liver fibrosis." (PMID 29403377, 2017). "Moreover, in NASH patients, serum level of TLR4 was able to predict liver fibrosis." (PMID 29118935, 2017). "Therefore, TLR4 is predicated to be involved in pathogenesis of hepatic fibrosis." (PMID 26785354, 2016). "Therefore, the interruption of TLR4 signaling could be as a target to suppress the activation of KCs and disrupt the progression of liver fibrosis." (PMID 26785354, 2016). "However, the functional significance of miR-146a-5p during the LPS/TLR4 mediated hepatic fibrosis process remains unclear." (PMID 27399683, 2016). "Furthermore, increased expression of TLR-4 on biliary epithelium in primary biliary cirrhosis after bile duct ligation on experimental studies suggests TLRs role in the development of chronic inflammation and liver fibrosis." (PMID 22114589, 2011). "This soluble receptor might provide a new biologic agent in the prevention and therapy of liver fibrosis and other diseases in which TLR4-mediated signal transduction plays a pathological role, such as in alcoholic liver injury and non-alcoholic steatohepatitis." (PMID 20964825, 2010). "The specific roles of TLR4 in Kupffer cells and HSCs during liver fibrosis were unknown." (PMID 20706677, 2010). "Thus, intestinal microflora-derived and translocated LPS participate in TLR4-mediated liver fibrosis, most likely due to increased intestinal permeability induced by intestinal dysbiosis, such as bacterial overgrowth, and disintegrity in the tight junction of intestinal epithelium." (PMID 20706677, 2010). "This elevated TLR4 activation, in turn, contributes to LSEC dysfunction by suppressing eNOS expression, potentially providing a microenvironment conducive to liver fibrosis progression and the exacerbation of portal hypertension." (PMID 41575990, 2026). "Aberrant Jagged1 activity from hepatocytes is likely to be mediated by TLR4-NFκB signaling and is necessary for Notch activation in NASH-induced liver fibrosis." (PMID 39747668, 2025). "Using hepatocyte-specific knockout approaches, TLR4 on hepatocytes has been shown to trigger innate immune responses that contribute to MASLD and MASLD-induced liver fibrosis." (PMID 40595432, 2025). "Isochlorogenic acid and chlorogenic acid can inhibit the protein expression of HMGB1 and TLR4, suppress the overexpression of α-SMA in HSCs, and prevent HSCs activation, thereby alleviating liver fibrosis." (PMID 41154556, 2025). "Large amounts of the non-protein glycosaminoglycan HA are deposited in the ECM in hepatic fibrosis, which can regulate cellular functions via CD44 and TLR4 expressed in both HSCs and macrophages." (PMID 40761743, 2025). "It is important to note that TLR4/NF-κB signaling strengthens the fibrogenic pathway of TGF-β, and its suppression is considered a therapeutic target in liver fibrosis." (PMID 39968080, 2025). "Another study showed that Dectin-1 also interacts with TLR4 and CD14 to alleviate liver fibrosis and oncogenesis." (PMID 39590166, 2024).
liver fibrosis (continued). "Our study shows that the TLR4, MyD88, p-IκB, and p-NF-κB protein expressions levels were considerably elevated in rats with BSA-induced liver fibrosis compared to the controls, while the CPhGs intervention effectively inhibited these changes (p < 0.05)." (PMID 39338312, 2024). "On the other hand, activation of multiple TLRs has been shown in complex diseases (e.g., activation of TLR3 and TLR4 in rheumatoid arthritis, and TLR4 and TLR9 in liver fibrosis)." (PMID 38951806, 2024). "Liver fibrosis was confirmed by trichrome staining and was accompanied by a significant increase in proinflammatory IL-6, TNF-α, TLR-2, and TLR-4 and a decrease in anti-inflammatory IL-10." (PMID 39000518, 2024). "Toll-like receptor 4 (TLR4) antagonists, LOXL2 inhibitors, and autotaxin (ATX) inhibitors are being investigated for their roles in liver fibrosis." (PMID 38397999, 2024). "Mechanistically, Dectin-1 activation led to the downregulation of TLR4 and its co-receptor CD14, thereby undermining TLR4 signaling in hepatic stellate cells and inhibiting liver fibrosis and oncogenesis." (PMID 39590166, 2024). "HSCs express CD44 and TLR4, and HSC activation upregulates the expression of CD44 in liver fibrosis." (PMID 36930869, 2023). "TLRs including TLR2, TLR3, TLR4 and TLR9 are expressed on hepatocytes, Kupffer cells, fibroblasts, neutrophils, dendritic cells and endothelial cells in the liver and activated in hepatic fibrosis liver tissue." (PMID 37122694, 2023). "Evidence continues to surface that links DAMP activated TLR4 signaling to the regulation and production of ECM proteins in hepatic fibrosis and to TM damage and ocular hypertension." (PMID 35912101, 2022). "Specifically, in a rat model of NASH, combining UDCA with losartan attenuated liver fibrosis, decreased intestinal permeability, and inhibited the expression of TGF-β1 and TLR4 with hepatic stellate cells activation." (PMID 36189347, 2022). "Further, the TLR4 antagonist JKB-121 is a long-acting small molecule and an effective treatment for the prevention of inflammatory injury and liver fibrosis in NAFLD patients." (PMID 35958576, 2022). "Breviscapine alleviated nonalcoholic steatohepatitis and liver fibrosis by inhibiting TGF-β-activated kinase 1 and toll-like receptor 4 (TLR4) / NF-κB signaling pathway to protect the liver and prevent the further development of liver disease to HCC." (PMID 35907976, 2022). "TLR4 signaling has been reported to induce HSC activation and liver fibrosis through many mechanisms." (PMID 34034779, 2021). "To further explore the possible antifibrogenic mechanism of KXRG in hepatic fibrosis, we examined the effects of KXRG on PDGF-stimulated intracellular pathways in HSCs, focusing on TGF-β and TLR4 signaling pathways." (PMID 34422075, 2021). "In addition, the study aimed at exploring the TLR4-TF-PAR1 signaling loop as a novel pathway that may be involved in liver fibrosis and the possible role of suppressing TF expression in blocking this loop as a form of cross-talk between coagulation, inflammation and fibrogenesis." (PMID 34045968, 2021). "As shown in the heatmap, inflammatory mediators were expressed significantly, with higher levels in the CCL4-induced liver fibrosis mice than in healthy controls (P value TLR-2 0.02, TLR-4 0.003, and TNF-α 0.03)." (PMID 34549998, 2021). "Thrombin was reported to produce a dual effect on liver fibrosis via action on PAR1 and through TLR4." (PMID 34045968, 2021). "Among those PPRs, the importance of TLR4 is well documented; indeed, TLR4 inhibition (TAK-242 or Serelaxin) has been shown to ameliorate injury and inflammation in rodent models of liver fibrosis, cirrhosis and ACLF." (PMID 33868313, 2021). "Similar results were shown in our CCl4 induced liver fibrosis model, as ACTA-2, TIMP-2 and Collagen-1 mRNA expression and Sirius red and α-SMA staining were similar between TLR4 KO and WT mice." (PMID 33391458, 2021).
liver fibrosis (continued). "Such bacterial products are ligands of endogenous Toll-like receptor 4 (TLR4) triggering inflammation responses involved in NAFLD, NASH and liver fibrosis." (PMID 33212947, 2020). "Therefore, CCl4, as a key and determinant factor in the pathological development of liver fibrosis induced by TLR4/NF-κB activation, was used to clarify whether DOP had potential anti-inflammatory and oxidative stress effects and determine the possible mechanism between them." (PMID 32226380, 2020). "Inhibition of Bambi by TLR4 enhances TGF- β signaling in HSC and thus has promoting effect on the augmentation of liver fibrosis." (PMID 32944845, 2020). "The pattern recognition receptor TLR4 and complements play important roles in the regulation of inflammation, HSC activation and liver fibrosis." (PMID 32283542, 2020). "TLR4 can activate NF-κB and JNK, promote the expression of IL-8 and MCP-1, enhance the inflammatory response and promote liver fibrosis." (PMID 32932919, 2020). "The inhibition of tTG activity through cystamine administration or gene knockout alleviated the level of TLR4, NF-κB pathway molecules, IL-33/ST2, and the severity of liver fibrosis resulting from Sj infection." (PMID 31200771, 2019). "Overwhelming endotoxin presumably stimulates TLR4 on the HSC, which enhances the production of extracellular matrix inducing liver fibrosis." (PMID 31726747, 2019). "Toll-like receptor 4 (TLR4) contributes to HCC initiation and progression, as well as liver fibrosis." (PMID 28423574, 2017). "Interestingly, although liver damage and cell division/death are more prominent in the double-deficient line, hepatic collagen contents as marker for liver fibrosis are reduced, implicating a beneficial role for TLR4 in liver injury but not in liver fibrosis in this model." (PMID 27391331, 2016). "Accumulating evidence has demonstrated the important role of LPS/TLR4 signal transduction pathway in the activation of HSC and immune cells during the hepatic fibrosis process." (PMID 27399683, 2016). "In CCl4-induced liver fibrosis animal model and ConA challenged mice, curcumin inhibits liver expressions of TLR2, TLR4, and TLR9." (PMID 25954568, 2015). "In the study of the treatment of liver fibrosis, curcumin is effective in preventing liver fibrosis partly because of reducing TLR2, TLR4 and HMGB1 expression by inhibiting pro-inflammatory mediators and HSCs activation." (PMID 25284457, 2014). "It is, therefore, demonstrated that the synergistic effects between Ang II and TGF-β1 during hepatic fibrosis doesn't only require the LPS-TLR4 signal pathway, but also up-regulation of HSC TLR4 expression by Ang II." (PMID 24155898, 2013). "For example, TLR4 signaling in hepatic stellate cells enhanced TGF-β secretion and hepatic fibrosis." (PMID 20520770, 2010). "Another study has shown that the gut microbiome can maintain intestinal immune homeostasis by altering Toll-like receptor 4 (TLR4) DNA methylation in intestinal epithelial cells (IECs), achieved through DNMT3 recruitment, a mechanism crucial to hepatic fibrosis and steatosis progression." (PMID 40166716, 2025). "In a thioacetamide-treated mouse model, the expression of liver fibrosis markers and inflammatory responses mediated by macrophages was suppressed after the inhibition of HMGB1, TLR4 and the assembly of NLRP3/ASC inflammasomes induced by LPS/ATP in mouse peritoneal macrophages." (PMID 40761743, 2025). "According to reports, TLR4 can promote the production of inflammatory factors (such as TNF-α and IL-1β) and affect the activation of hepatic stellate cells, thus exacerbating liver fibrosis and inflammatory reactions in alcohol-induced liver injury by activating Kupffer cells." (PMID 39861457, 2025). "Gentiopicroside has been reported to inhibit the TLR4 and NLRP3 signaling pathways in macrophages, which brought the release of inflammatory factors, improvement of hepatocyte pyroptosis, and alleviation of the hepatic fibrosis." (PMID 40761743, 2025).
liver fibrosis (continued). "In this study, we randomly divided mice into the control, model, FAE high-dose, FAE medium-dose, and FAE low-dose groups to analyze the pathological changes in the hepatic fibrosis and levels of the α-SMA, collagen 1, Nuclear Factor Kappa B (NF-κ B), Toll Like Receptor 4 (TLR4)." (PMID 39974825, 2024). "Additionally, it can hinder the activation and proliferation of hepatic stellate cells by targeting the toll-like receptor 4 (TLR4)/nuclear factor kappa B (NF-κB) signal pathway, thereby slowing down the progression of liver fibrosis." (PMID 39595654, 2024). "Moreover, Gm-SGPP prevents hepatic fibrosis by down-regulating the TLR4-mediated TGF-β/Smad pathway, and to the best of our knowledge, this is the first report showing that Gm-SGPP prevents hepatic fibrosis by reducing cholesterol accumulation." (PMID 39057397, 2024). "Overall, the research suggested that EPO could prevent TAA-induced hepatic fibrosis through upregulating the PI3K/Akt signaling cascade and downregulation the TLR4 downstream axis." (PMID 37649466, 2023). "Thus, activation of the eNAMPT/TLR4 inflammatory pathway contributes to NAFLD severity and NASH/hepatic fibrosis." (PMID 36809677, 2023). "In addition to chlorogenic acid, isochronogenic acid A (ICQA) reduces liver fibrosis and the expression of high-mobility group box 1 (HMGB1) and TLR4, alleviates NF-κB p65 nuclear translocation, and inhibits p-IKB expression." (PMID 38202710, 2023). "Finally, although the contribution of TLR4/NFkB signaling to NASH and hepatic fibrosis is well known, in future studies, we will validate the protective role of ALT-100 mAb via eNAMPT/TLR4 utilizing TLR4 knockdown or inhibitors." (PMID 36809677, 2023). "Emerging evidence suggested that MSCs-Exo could inhibit liver fibrosis by multiple processes, including autophagy, TGF-β/smad, Wnt/β-catenin, LPS/TLR4, EMT/ERK1, PPARγ, NF-κB pathway." (PMID 36698192, 2023). "Here, we observed that the macrophage was the major cell type that underwent NLRP3 inflammasome-dependent pyroptosis in liver fibrosis, which could be mediated by S100A8-induced Toll-like receptor 4 (TLR4)/NF-κB activation and ROS generation." (PMID 36429008, 2022). "In previous study, decreased LPS production from the gut by OCA treatment activated TLR-4 and TLR-9, thus promoting inflammation, steatosis, and fibrosis, which might have contributed to reduced liver fibrosis." (PMID 35770078, 2022). "TLR4-IFN-γ-MSCs induced Th1 to restore Th1/Th2 balance and alleviate liver fibrosis." (PMID 34072224, 2021). "A recent study confirmed that TLR4 signaling, activated in hepatic stellate cells rather than in Kupffer cells, was more important for the development and progression of hepatic fibrosis." (PMID 34361075, 2021). "The regulation of TLR4 signaling and COX2/PGE2 with a consequent decrease in liver fibrosis may represent a potential therapeutic approach for hepatic granuloma caused by Sj infection." (PMID 34034779, 2021). "Both TLR4 signaling and the COX2/PGE2 axis are involved in HSC activation and hepatic fibrosis." (PMID 34034779, 2021). "Previous studies have shown that in the development process of liver fibrosis, LPS can indirectly or directly stimulate the activation of HSCs and induce the expressions of ECM components, which may involve TLR4/NF-κB, autophagy and other signaling pathways." (PMID 34987404, 2021). "The fact that IAP supplementation was not able to attenuate liver fibrosis in TLR4 KO mice, confirms the important role of LPS in this setting." (PMID 33391458, 2021). "Development of LPS mimetics that do not engage CD14/TLR4 but still can act on activated HSCs will be a novel way to reverse these cells to the non-fibrogenic phenotype for treating liver fibrosis." (PMID 32373617, 2020). "Therefore, the investigation of potential inhibitors of both TLR4 signaling and TGF-β1 signaling represents an attractive strategy for the treatment of liver fibrosis." (PMID 32296336, 2020).
liver fibrosis (continued). "This confirms the role of the TLR4/NF-κB pathway in mediating HSC activation and hepatic fibrosis." (PMID 32283542, 2020). "Furthermore, we detected the levels of TLR4, NF-κB, TNF-α, TGF-β, IL-10, α-SMA, and collagen I to study the degree of liver fibrosis in rats." (PMID 32226380, 2020). "Altogether, these results suggested treatment with TLR4-activated MSC alleviated liver fibrosis, without increasing inflammatory response." (PMID 32503644, 2020). "During cholestasis, excessive inflammatory responses can activate the TLR4 signaling pathway, which promotes NF-κB activation to secrete more proinflammatory cytokines, like TNF-α and IL-6, to aggravate inflammatory damage and liver fibrosis." (PMID 31827690, 2019). "Also, in vivo in a setting of hepatic fibrosis in rats reduced ALT, AST, IL-6 and HMGB1 values were found after EP treatment compared to the control group accompanied by decreased mRNA levels of TLR4 and NF-κB." (PMID 29420582, 2018). "In liver, TLR4 is expressed by all parenchymal and non-parenchymal cell types, and contributes to tissue damage, liver fibrosis, NASH, and HCC progression." (PMID 30034633, 2018). "Moreover, LBP is an acute-phase protein that binds to lipopolysaccharide to induce the downstream TLR-4 signaling pathways of innate immunity and the inflammatory pathway of NASH, liver fibrosis and metabolic related diseases." (PMID 30458048, 2018). "Compared with wild-type mice, Tlr4 (−/−) mice showed a higher survival ratio and a higher extent of liver fibrosis, but the difference was not significant (data not shown)." (PMID 29321784, 2017). "Therefore, CA increases miR-29b-3p to inhibit the HMGB1/TLR4/NF-κB pathway, thereby attenuating BDL-induced liver fibrosis." (PMID 29403377, 2017). "The novel self-reinforcing molecular feedback loop between the TLR4 pathway and TGM2 may represent a potential new target in Sj infection-induced liver fibrosis and even other related liver diseases." (PMID 29321784, 2017). "TLR4 signaling in HSCs, but not in Kupffer cells, is crucial for the development of liver fibrosis induced by alcohol, CCL4, and viral infection." (PMID 29321784, 2017). "In summary, our data indicate that the miR-29b-3p/HMGB1/TLR4/NF-κB signaling pathway might be essential for liver fibrosis and that CA could be a promising therapeutic agent in liver fibrosis by modulating the miR-29b-3p/HMGB1/TLR4 signaling pathway." (PMID 29403377, 2017). "Additionally, it has been demonstrated that TLR4-mutant mice critically attenuated fibrosis in the bile duct ligation (BDL) model and antibiotic treatment suppresses liver fibrosis." (PMID 26785354, 2016). "Recent studies indicated that TLR4 enhanced TGF-β signaling and hepatic fibrosis." (PMID 25984739, 2015). "Furthermore, dioscin was effective in suppressing the TLR4/MyD88/NF-κB signaling pathway to inhibit HSCs activation and reduce ECM accumulation for attenuating liver fibrosis in vivo and in vitro." (PMID 26655640, 2015). "Together, these data indicated that dioscin-attenuated liver fibrosis via down-regulating TLR4, not LPSBP." (PMID 26655640, 2015). "We report that HSCs appear to play an important role in linking the process of hepatic granulomatous to hepatic fibrosis via NF-κB signaling, with miR-146 potentially modulating this process by targeting TRAF6, a key adapter molecules in the TLR4/NF-κB pathway." (PMID 25116007, 2014). "p-hydroxycinnamic acid, a natural phenolic compound, was reported to suppress the TLR4/NF-κB signaling pathway, reduce IL-1β precursor expression, and attenuate NLRP3 inflammasome activation in a mouse model of high-fat, high-sucrose diet-induced liver fibrosis, thereby inhibiting HSCs activation." (PMID 40661312, 2025).